PPARG (peroxisome proliferator activated receptor gamma)
Diseases named in the same sentence as PPARG in open-access papers (continued):
Sharing a sentence is not in itself a finding about the gene and the disease.
cancer (continued). "TZDs have been touted as potential anti-cancer agents, and differences in the expression of PPARG within tumors could aid in the personalization of therapeutic regimens." (PMID 32894083, 2020). "The first meta-analysis used here for illustrative purposes investigated the roles of the PPARγ rs1801282 polymorphism and the intake of NSAID in developing cancer, which collected eight studies involving 4269 cases and 5903 controls, and all studies consisted of stratified data." (PMID 32513119, 2020). "In this study, however, PPARG was found to have low expression in the majority of TCGA cancers." (PMID 33029111, 2020). "Increasing evidence points towards an important role of PPARγ in cancer." (PMID 31936729, 2020). "According to our statistical results, NSAID usage was associated with a decreased risk of cancer among PPARγ rs1801282 wild-type homozygous (CC) individuals but not among mutant-type allele carriers (CG or GG)." (PMID 32513119, 2020). "Thus, MTMR7 is a positive regulator of PPARγ, and its mimicry by synthetic peptides overcomes inhibitory mechanisms active in cancer cells possibly contributing to the failure of clinical studies targeting PPARγ." (PMID 32522977, 2020). "In another study, α-ESA, considered as a PPARγ agonist like rosiglitazone, as well as GLA, suppressed cell growth in BC cell lines by activating PPARγ nuclear compartmentalization, which suggested that nuclear localization of PPARγ plays a role in anti-cancer functions in BC." (PMID 32085795, 2020). "Also, our study showed that HD-SB induced cancer cell apoptosis via EGFR/PPARγ/PI3K/AKT pathway and lays a solid foundation for further studies of the herb pair in cancer treatment." (PMID 32265701, 2020). "However, several studies also showed that PPARγ expression was more marked in carcinoma tissues of several types of human malignancies than in normal tissues." (PMID 33197888, 2020). "Several previous studies suggested that the upregulation of PPARG might induce chemosensitivity in human carcinomas." (PMID 32373170, 2020). "This correlation is lost when certain angiogenic factors, namely, basic fibroblast growth factor and platelet-derived endothelial growth factor, are coexpressed in the tumors, indicating a possible role of PPARγ in angiogenesis in cancer progression by interacting with these growth factors." (PMID 30925918, 2019). "Moreover, in 1997, the first published reports highlighted PPARγ as a novel cancer therapeutic target regulating the differentiation of cancer cells." (PMID 31337851, 2019). "Thus, our study suggests that PPARG overexpression, as well as treatment with its agonist, can be potentially explored to radiosensitise certain otherwise resistant cancer types, e.g., NSCLC." (PMID 31263479, 2019). "In conclusion, our data supports the idea that PPARγ plays a key role in regulating immune function and that PPARγ ligands may exert anti-cancer activity through an improved anti-tumor immune response." (PMID 31212694, 2019). "The role of PPARγ agonists remains unclear in cancer cells, even if their role is well understood in the regulation of differentiation and stemness programs." (PMID 31311204, 2019). "In conclusion, the novel FABP5 inhibitor dmrFABP5 suppresses the malignant progression of CRPC by blocking fatty acid-stimulation of PPARγ and thereby it curtails its up- or down-regulating effect on the down-stream cancer-promoting or -suppressing genes in the nude mouse model of CRPC." (PMID 31258834, 2019). "For all this, PPARG has been proposed as a promising therapeutic target for cancer treatment." (PMID 31100982, 2019). "The PPARγ pathway was shown to be relevant in cancer earlier." (PMID 31412918, 2019). "Moreover, PPARγ is involved in the regulation of cell growth and differentiation in normal and cancer tissues." (PMID 31546785, 2019).
cancer (continued). "Taken together, PPARG agonism was found to invigorate the radiosensitising effect and hence its use in combination with radiotherapy is expected to enhance sensitivity in otherwise resistant cancer types." (PMID 31263479, 2019). "Furthermore, multiple studies are investigating the therapeutic potential of PPARγ modulators as innovative cancer therapy." (PMID 31511776, 2019). "However, several works on cancer and neurodegenerative diseases have shown that PPARγ activation inhibits the PI3K/AKT/mTOR signaling pathway." (PMID 31993046, 2019). "However, PPARγ was recently shown to play a significant role in decreasing cell proliferation and inducing differentiation and apoptosis in many types of cancer." (PMID 30902074, 2019). "The mechanism of PPAR-γ and PGC-1α in cancer is still contradictory with dual effects, of which the molecular interactions of PPARγ and PGC-1α with other transcriptional factor are necessary to be further investigated to clarify the role of PPARγ and PGC-1α in CRC." (PMID 31652933, 2019). "Besides that, PPARγ gain more pros than cons with the studies that demonstrate the activity of their ligands as cancer suppressors." (PMID 31555078, 2019). "Nevertheless, interest in the association between PPARγ agonists and melatonin in cancer therapy is not new." (PMID 31331376, 2019). "The action of PPARγ agonists remains unclear in cancer cells even if their role is well understood in the regulation of differentiation and stemness programs." (PMID 31331376, 2019). "In addition, the immunofluorescence staining showed that rosiglitazone induced translocation of PPARγ from cytoplasm into nucleus indicating marked PPARγ activation in 5637 cancer cells." (PMID 30845932, 2019). "The expression of PPARG is differential in normal versus cancer cells." (PMID 31263479, 2019). "However, the role of PPARγ in cancer is controversial, with studies showing either pro- or anti-neoplastic effects." (PMID 31138783, 2019). "Additionally, PPARγ agonists have been pointed as potential pharmacological tools to suppress cancer progression." (PMID 31555078, 2019). "More recently, pharmacologic evidence suggests a potential anti-cancer activity for PPARγ agonists." (PMID 31212694, 2019). "High transcript levels of PPARγ could stimulate angiogenesis in various carcinoma through increasing VEGF expression." (PMID 31333806, 2019). "Here we found the effect of PPARγ on genes that were implicated in both LOAD and cancer." (PMID 29723294, 2018). "Thus, this review updates the role and action mechanisms of PPARγ in cancer since our review published in 2012." (PMID 29599799, 2018). "In several diseases, the WNT/β-catenin pathway and PPARγ act in an opposite manner as in cancers, such as gliomas, neurodegenerative diseases, such as Alzheimer’s disease, amyotrophic lateral sclerosis, multiple sclerosis, age-related macular degeneration, and fibrosis processes." (PMID 29706964, 2018). "Thus, this review updates the progress in understanding the role and molecular mechanisms of PPARγ in cancer." (PMID 29599799, 2018). "Conversely, a significant reduction in the expression of PPARγ has been observed in many cancers." (PMID 29706964, 2018). "Consecutively, many experimental data indicate that PPARγ agonists may modulate multifold biologic hallmarks in cancer: Cell cycle, differentiation, proliferation, apoptosis, and oxidative stress, innate immunity, angiogenesis, and inflammation." (PMID 30424016, 2018). "Conversely, simultaneous activation of LATS2 and PPARγ may instigate a metabolic catastrophe, particularly in cancer cells with high energy demands, possibly by increasing mitochondrial burden." (PMID 30456386, 2018). "Dampening of PPARγ activity might reflect an energetic necessity of highly glycolytic LATS2-depleted cancer cells." (PMID 30456386, 2018).
cancer (continued). "The use of PPARγ agonists in cancers could reduce both ROS production and chronic inflammation leading to a decrease in the WNT/β-catenin pathway and then an inhibition of carcinogenesis processes." (PMID 29706964, 2018). "PPARγ is involved in lipid metabolism and has recently been shown to play a significant role in cell proliferation, differentiation, and apoptosis in many types of cancer." (PMID 29530037, 2018). "On the other hand, a significant antiproliferative effect of TZDs on several types of cancer has been reported, together with the observation that some PPARγ agonists seem to contribute to improve the chemical sensitivity of certain cancers to standard chemotherapeutic agents." (PMID 30123711, 2018). "RXR and PPARγ are potential candidate targets for cancer prevention and treatment." (PMID 29740162, 2018). "Few studies have observed that high PPARγ agonists can increase cortisol levels in cancers." (PMID 29659554, 2018). "However, there was little report supporting that PGC-1α expression directs PPARγ activity in cancer." (PMID 29599799, 2018). "PPARγ also plays a role in the regulation of cancer cell growth." (PMID 30575780, 2018). "In addition, activating PPARγ by its other ligands appears to possess both pro- and anti-cancer activities." (PMID 29163813, 2017). "PPARγ activation exhibits inhibitory effect on cancer cells in vitro." (PMID 28656106, 2017). "Also, given that PPARγ is a master regulator in lipid metabolism, we wondered how PPARγ-mediated lipid metabolism would be involved in regulating REDOX balance in cancer." (PMID 29137280, 2017). "PPARγ, at the crossroads of physiological and pathological processes such as metabolic control and adipogenesis, inflammation, apoptosis, and cancer, is particularly interesting for the study of the effects of nsSNPs on its structural stability, thermodynamic, and dynamic properties in solution." (PMID 28208577, 2017). "In addition, pharmacological inhibition of PPARγ with antagonist T0070907 significantly increased the expression of key cancer immunity-enhancing inflammatory factors including CCL2 and IL8 in the PPARG-amplified 5637 cells." (PMID 28740126, 2017). "The PLC/PPARγ connection has both an anti-inflammatory and anti-cancer potential." (PMID 29020973, 2017). "The difference in the levels of PPARγ expression between the two cancer cell lines may account for this observation, as the 5637 cell line has a considerably higher PPARγ expression than UMUC-3 cell line." (PMID 28348577, 2017). "PPARγ plays an important role in inflammation, glucose metabolism and cancer." (PMID 28948004, 2017). "PPARγ belongs to a nuclear receptor family, along with PPARα and β/d, and is highly expressed not only in adipocytes during differentiation but also in various cancer cells." (PMID 28642874, 2017). "Being at the crossroads of multiple diseases, PPARG may be a key component for understanding the pathophysiology of cancer." (PMID 29254243, 2017). "In particular, the gene expression for lipid uptake and storage was induced in the xenograft model upon pioglitazone administration, suggesting that PPARγ activation might be more involved in systemic lipid mobilization for cancer growth." (PMID 29137280, 2017). "As its influence on cancer cells has been extensively reviewed elsewhere, this review will focus on how the microenvironment may be affected by PPARγ's anti-inflammatory function." (PMID 28316613, 2017). "Previously, several studies demonstrated that quercetin inhibited inflammation, enhanced immune function and promoted apoptosis by modulating key pathways regulating cancer, such as, prostaglandin G/H synthase 2, interleukin (IL)-2, peroxisome proliferator activated receptor gamma and caspase-9." (PMID 28099904, 2017). "In a subgroup analysis by the ethnicity, evidence of significant association between PPARG c.1347C>T polymorphism and increased risk of cancer were also found among Asians, and mixed populations, but not Caucasians." (PMID 29254243, 2017).
cancer (continued). "5-LO, mPGES1, PPARα, and PPARγ are also potential drug targets for anti-cancer therapies." (PMID 26887049, 2016). "PGJ polyphenols can regulate the activation of PPARγ in several cancer cells." (PMID 27706074, 2016). "Previous studies largely focused on the direct effects of PPARγ on cancer cells." (PMID 27692066, 2016). "Besides having prodifferentiation, antiproliferative, and proapoptotic effects, PPARγ agonists have been shown to prevent cancer cells from acquiring the migratory and invasive capabilities essential for successful metastasis." (PMID 27698657, 2016). "Furthermore, we can find in the literature compelling evidence for PPARG having antineoplastic actions in colon, prostate, breast, and lung cancers, which happen to be the most prevalent forms of cancer in occident." (PMID 27579030, 2016). "Intriguingly, PPARγ agonists have also been found to be of interest in cancer treatment." (PMID 27313600, 2016). "To further examine whether Gpr132 is a functional PPARγ target in macrophage that is required for PPARγ cancer regulation, we conducted pharmacological and genetic experiments." (PMID 27692066, 2016). "This uncovers Gpr132 as not only a novel key PPARγ target but also a new cancer therapeutic target." (PMID 27692066, 2016). "Although substantial studies on PPARγ have focused on the mechanisms by which PPARγ regulates glucose and lipid metabolism, reports over the past several years have suggested that PPARγ might play additional roles in inflammatory response and cancer." (PMID 27323819, 2016). "PPARG agonist can also enhance VEGF expression in cancer cells, as some studies reveal." (PMID 27579030, 2016). "To assess the functional significance of macrophage PPARγ in the pharmacological effects of rosiglitazone, we treated mf-g-KO mice and littermate controls with rosiglitazone or vehicle control starting four days after cancer cell injection." (PMID 27692066, 2016). "On this basis, PPARγ presents an attractive molecular target for cancer chemoprevention." (PMID 26516762, 2015). "In particular, we predict isoform switches that affect the encoded protein for the cancer drivers CCND3, MYH11, MITF, RALGD5, ABI1, PRDM1 and PPARG, which may have implications for targeted therapy development." (PMID 25578962, 2015). "In addition, expression of PPARγ nuclear receptors has been found in many cancer cell lines such as the fibroblast cell line, hepatocyte cell lines and epithelial cell lines of the breast and colon." (PMID 25870831, 2015). "These contrasting results suggest that PCa may undergo the trans-differentiation process from the epithelial type to the mesenchymal type of cancer after TR4 was altered in the PPARG-deleted prostate cells." (PMID 25859557, 2015). "This suggests that TZDs would be applicable to the tumors in which the PPARγ expression with no mutation of sumoylation sites should be assessed for clinical application of TZDs to the cancer patients." (PMID 26244663, 2015). "It is overexpressed in many types of cancer cells, suggesting that regulation of PPARγ may also affect carcinogenesis." (PMID 26309807, 2015). "Peroxisome proliferator-activated receptor γ (PPARγ) is a member of the nuclear hormone receptor superfamily of ligand-activated transcription factors that are involved in regulation of energy metabolism, cancer development and anti-inflammatory response." (PMID 26492315, 2015). "As PPARG has also been shown to regulate certain processes in cancer development, it might be a possible additional target in the treatment of cancer." (PMID 26697060, 2015). "An expanding body of evidence supports the hypothesis that activation of signaling pathways regulated by PPARγ may provide an effective strategy to prevent and/or treat cancer." (PMID 26516762, 2015). "To address whether the mutations found in our study could be causally implicated in ESS development, we queried the cancer Gene Census and found four mutations (SRGAP3, EBF1, IRF4 and PPARG)." (PMID 26429873, 2015).
cancer (continued). "Therefore, from these studies, PSF and PPARγ appear to be two attractive targets for the development of novel cancer treatments." (PMID 26309807, 2015). "Upregulation of PPARγ may be an early event in tumorigenesis and a marker for differentiated cancer lesions." (PMID 25866814, 2015). "In addition to its metabolic and anti-inflammatory properties, PPARγ also modulates proliferation and apoptosis of many cancer cell types, and is expressed in many human tumors including lung, breast, colon, prostate, and bladder cancer." (PMID 25083916, 2014). "Hence determining possible crosstalk between PPARγ and its ligand in cancer is critical for the development of more effective therapy." (PMID 25119466, 2014). "Peroxisome proliferator-activated receptor γ (PPARγ), a member of the nuclear receptor superfamily, is a ligand-dependent transcription factor whose activation results in growth arrest and/or apoptosis in a variety of cancer cells." (PMID 25119466, 2014). "As natural and synthetic PPARγ activators have been found to inhibit cancer cell growth in vitro and in animal models, PPARγ might also be a target for new cancer therapies." (PMID 25083916, 2014). "Activation of PPARγ could possibly be an approach to induce differentiation in cells thereby inhibiting proliferation of a variety of cancers." (PMID 23431283, 2013). "Furthermore, thiazolidinediones (TZDs), a class of anti-diabetic drugs and synthetic ligands for PPARγ, were also utilized in anti-cancer therapies." (PMID 24204697, 2013). "It is known that telmisartan has an anti-cancer activity as a PPARγ agonist." (PMID 23451083, 2013). "It has been reported that PPARγ agonists induce ROS production in multiple types of cancer cells." (PMID 24023668, 2013). "A previous study demonstrated that the activation of PPARγ is able to inhibit cancer cell growth, and this may be due to the inhibition of angiogenesis." (PMID 24137293, 2013). "PPARγ is an interesting target for cancer therapy not only because of its elevated expression in tumors, but also because PPARγ activation results in decreased cell proliferation, decreased G0/G1 to S phase progression, increased terminal differentiation, and apoptosis." (PMID 23409107, 2013). "In some cancer cells, SO signal through PPARγ to inhibit proliferation." (PMID 23637839, 2013). "We have previously reported that inhibition of EGFR signalling axis and activation of PPARγ axis are both effective in significantly inhibiting proliferation of human carcinoma cells through different pathways, in part converging to PI3K/Akt, cyclin D1, and cyclin-dependent kinase inhibitors." (PMID 23409107, 2013). "The realization that PPARγ is, at least in part, the mediator of their effect has contributed in bringing the receptor to the spotlight as a potential pharmacologic target in diseases beyond diabetes such as cancer." (PMID 23049538, 2012). "Anyway, the role of PPARγ in the neoplastic diseases of the gastrointestinal tract remains controversial, as this nuclear receptor shows dissimilar growth-suppressive effects in different cancers." (PMID 23028383, 2012). "Some reports describe that PPARγ affects control of cancer stem cells." (PMID 23316217, 2012). "Although emerging data suggest that PPARγ and PPARγ ligands exert antitumorigenic effects on cancer cells, there is evidence that activation of PPARγ may also have deleterious, protumorigenic effects." (PMID 22934105, 2012). "Together, these studies indicate that PPARγ may act as a tumour suppressor and that specific agonists could be used in cancer prevention." (PMID 23024649, 2012). "It will also address the unanswered question as to whether PPARG epigenetic deregulation contributes to the establishment of “precancerous lesions” or very early cancer developmental stages." (PMID 22848209, 2012). "Therefore, the dosage of PPARγ agonists for cancer therapy must be carefully defined in clinical trials." (PMID 22693486, 2012).